CXCL1 (C-X-C motif chemokine ligand 1)
Diseases named in the same sentence as CXCL1 in open-access papers (continued):
Sharing a sentence is not in itself a finding about the gene and the disease.
infection (continued). "LysM-Myd88−/− mice showed a strongly impaired neutrophil influx into the bronchoalveolar space 6 hours after infection with Klebsiella, together with markedly reduced local concentrations of neutrophil attracting mediators such as TNF-α, CXCL1 and CXCL2." (PMID 25254554, 2014). "To test this idea, we measured expression of KC (Cxcl1), a CXC chemokine that recruits neutrophils to sites of infection." (PMID 24787713, 2014). "The kinetics of TNF-α, CXCL1, IFN-γ and IL-6 showed a similar time dependent increasing trend with peak expression at 72h of L2-MHV3 infection." (PMID 24058536, 2013). "MIP-2 (CXCL2) and KC (CXCL1) belong to the CXC chemokines, which are potent chemoattractants involved in neutrophil recruitment to the site of infection." (PMID 24039581, 2013). "To further check how Fas and FasL influence the cytokine and chemokine production in vivo we assessed vaginal lavages for the production of chemokines (CXCL1, CXCL9 and CXCL10) and interleukins (IL-1β and TNF-α) at 3 and 7 day of infection." (PMID 23922974, 2013). "Levels of IL-1β, CXCL-1 and CXCL-2 were higher in 5-LO−/− mice 24 h after infection compared with WT mice." (PMID 23991239, 2013). "Similarly, a number of chemokines known to recruit leukocytes to infection sites were upregulated by MØs and DCs during Bb infection, but many of these were suppressed in the presence of Bb-elicited IL-10, particularly the neutrophil-recruiting chemokines such as KC (CXCL1) and MIP-2α (CXCL2)." (PMID 24367705, 2013). "Addition of Bb induced up-regulation of transcript levels for all chemokines assessed, including CXCL1, CXCL2, CCL2, CCL3, CCL4, and CCL5 by MØs and DCs as early as 4h post-infection." (PMID 24367705, 2013). "The RV/NTHi group showed a significant reduction in chemokine levels of KC/CXCL1 and MIP-2/CXCL2 compared to the sham/NTHi group at 6 and 24 h post-NTHi infection." (PMID 23055935, 2012). "Airway levels of CXCL1, CCL2, CCL3, CCL5, IFNγ, IL-6, and TNFα were measured 3 and 6 days after infection." (PMID 22496659, 2012). "Rather, RTD-1 administration appeared to protect infected animals by reducing pulmonary inflammation and suppressing IL-1α, IL-1β, IL-6, IL-12, CXCL1 (KC), CCL2 (MCP-1), CCL3 (MIP-1α), and CCL5 (RANTES) 2–4 days post-infection." (PMID 23236475, 2012). "Of the chemokines, the functional murine IL-8 homologue KC/CXCL1 and MIP-2/CXCL2 were both markedly increased in CSF, brain homogenate and blood at 30 hours after infection." (PMID 22455545, 2012). "CXCL-1 and MCP-1 are chemokines important for the recruitment of immune cells to sites of tissue injury and infection." (PMID 23226424, 2012). "The list of genes with the greatest induction following Mtb:Δ-sigH infection at this time-point included CXCL1 (120-fold), PTGS2 (100-fold), CXCL6 (75-fold), CCL2 (53-fold), CXCL3 (40-fold), CXCL1 (43-fold) and CCL2 (38-fold) CCL5 (35-fold)." (PMID 22235255, 2012). "Only CXCL10 expression was significantly attenuated in TLR4 mutant mice at day 3 post-infection, whereas the majority of mediators, including CCL2, CXCL1, and IL-1β were similar between TLR4 mutant and WT mice across all time points examined." (PMID 21496301, 2011). "In contrast, the chemokines CXCL1 and CXCL2, by binding to CXCR2, promote rapid release of neutrophils from the bone marrow, thereby elevating blood neutrophil counts during infection or during G-CSF-induced neutrophil mobilization." (PMID 21738479, 2011). "Following experimental infection with the neurotropic viruses including the JHM strain of mouse hepatitis virus (JHMV) or Theiler's murine encephalomyelitis virus (TMEV), both CXCL1 and CXCL2 are up regulated within the CNS." (PMID 20596532, 2010). "Significantly (p≤0.01) elevated mRNA transcripts for both CXCL1 and CXCL2 were observed throughout infection compared to sham-infected control mice, and expression was independent of viral load." (PMID 20596532, 2010).
infection (continued). "There was a good correlation between the levels of CXCL1 and CXCL2 in the lungs(B and FigS2A) and the recruitment of neutrophils after infection with 104and 106 PFU." (PMID 21079759, 2010). "The increased secretion of the chemokines CXCL1 and CCL20 is particularly important for attracting granulocytes to sites of infection." (PMID 20877575, 2010). "Transcript levels for various cytokines/chemokines (KC [CXCL1], MCP-1 [CCL2], MIP-1α, IFN-γ, IL-4, IL-5, IL-6 and IL-10) were determined in lungs of infected mice on days 1, 6 and 9 post-infection." (PMID 20661429, 2010). "Both CXCL1 and CXCL2 were expressed at significantly higher levels after infection with HAdV-D53 than with HAdV-D22." (PMID 19492050, 2009). "However, comparable levels of TNF, IL-6, IL-10, CXCL1, CCL3, GM-CSF, and G-CSF were observed upon CRWT and CRM12 infection." (PMID 40599135, 2025). "Furthermore, the levels of CXCL1, IL-6, and TNF-α in the culture supernatants were increased by EV-A71 infection." (PMID 39679722, 2025). "Many up-regulated genes are closely related to inflammation and immune responses, such as CCL20, IL6, CXCL1, CSF1R, CCR5, TNFRSF8, indicating that mice infected N. farcinica via these two infection routes may lead to robust inflammatory response." (PMID 40723822, 2025). "Fibroblasts synthesize pro-inflammatory cytokines such as IL-6, interferon-β (IFN-β), and tumor necrosis factor alpha (TNF-α), as well as chemokines like C-X-C motif chemokine ligand 1 (CXCL1), and secrete growth factors and metalloproteinases that support tissue repair after infection." (PMID 41305634, 2025). "In PCLS, where neutrophils are scarcely present, an increased expression of pro-inflammatory cytokines and chemokines related to neutrophil recruitment and activation such as CXCL1, CCL3, or IL-17A was measured, particularly in PCLS of old mice upon infection with D61." (PMID 38178102, 2024). "Baseline concentration of CXCL1 in the supernatant of lung discs without infection and treatment were considerably high and required serial dilutions to test successfully." (PMID 39605594, 2024). "CXCL1, CXCL2 and CXCL8 produce a local inflammatory response when infection or injury occurs." (PMID 39656442, 2024). "The positive correlation with CXCL1, CXCL16, and CCR1 indicated that PGK1 may contribute to the recruitment of immune cells, such as macrophages and T cells, to the site of infection or inflammation." (PMID 39712033, 2024). "Furthermore, tissue-resident macrophages can also express CXCL1, CXCL2, and various leukotrienes in response to infection." (PMID 38352492, 2024). "Similarly, we observed significant increases in IL-17, G-CSF, CXCL1, CCL2, CCL3, CCL4, and CCL11 production in 5-LO−/− mice, compared to C57BL/6 mice, at day 7 post-infection." (PMID 39082787, 2024). "Matching the data collected during the physical characterization of the NTHi-NHNE infection, expression levels of key chemo- and cytokines (e.g. CXCL8, IL-6, IL-1β, CCL3, CXCL1 & CXCL2) and genes involved in ECM remodelling and inflammation (PLAU, Serpine1, MMP9) increased further on day14." (PMID 38990812, 2024). "When macrophages detect microbial products, they initiate the inflammation program, producing chemokines and cytokines (such as IFNS, CXCL1, CCL2, TNFA, CXCl2, IL1B) necessary for recruiting leucocytes and upregulating neutrophil-killing capacity to resolve the infection." (PMID 39298265, 2024). "Therefore, to assess the role of CXCL1, CXCL2, CXCL3, and CXCL5 in neutrophil trafficking during infection with C. violaceum, we used a CXCR2 inhibitor." (PMID 38352492, 2024). "Here, we demonstrated that macrophages derived from Smurf1−/− mice secreted increased levels of the proinflammatory mediators TNF and CXCL1 in vitro, and the lungs from Smurf1−/− mice presented higher ratios of macrophages and neutrophils positive for TNF and iNOS upon infection with MHV-A59." (PMID 39452742, 2024).
infection (continued). "Infection triggered an increase in neutrophil accumulation in the liver; these cells produced TNF-α (significantly higher in females after infection), CCL2, and CXCL1, and the percentage of neutrophils producing CXCL1 was significant higher in males and females compared to uninfected mice." (PMID 38179044, 2023). "Additionally, pro-inflammatory cytokines, including MIF, PAI-1, IL-18, CXCL1, CXCL12 and IL-8, were statistically decreased (P < 0.05) in 10−6 M 1α,25(OH)2D3-pretreated A549 cells by 12 h post-infection." (PMID 36758060, 2023). "Levels of proinflammatory chemokines and cytokines CXCL1, CCL5, IFN-γ, IL-1β, CXCL10, IL-17, TNF-α and IL-6 were also assessed in the brain, spleen and liver of MAYV-infected mice throughout the infection." (PMID 36902230, 2023). "We hypothesize that a reduced expression of CXCL1 by B lymphocytes may, in part, help to explain why BTHS boys suffer from infections even when neutrophil counts are at or near normal levels." (PMID 37237543, 2023). "Also, molecules such as TIMP-1, KC (CXCL1), and MIP-1 alpha (CCL3) showed inhibition upon E. japonica- infection in MyD88-independent manner." (PMID 38022511, 2023). "The basal compartment CXCL1 levels increased at both time points for infection with live (“fit” and to a slightly higher extent for “non-fit”) parasites, but did not come close to the levels induced by the lysed trophozoites." (PMID 37141303, 2023). "Mtb-induced CXCL1 and CXCL2 could play important roles in recruiting neutrophils to sites of infection and control the early infection." (PMID 36315280, 2023). "Considering the increase in cx3cr1 expression found in our study and the regulation of CXCL1 regulation by SCFAs23, we hypothesize that SCFA feeding shaped the generation and migration of patrolling monocytes to the liver during the infection." (PMID 37865711, 2023). "Notably, our results showed an upregulated transcriptional expression of cytokines (IL-1β, IL-6 and TNF-α), adhesion molecules (VCAM-1, ICAM-1) and chemokines (CXCL1 and CXCL2) after infection in both brain cortex and hippocampus." (PMID 36778380, 2023). "Furthermore, upon infection with Shiga-toxin-producing enterohemorrhagic E. coli, neutrophil recruitment was dependent on TNF-α, CXCL1 and CXCL2 produced by tissue-resident macrophages and was directly associated with kidney injury and poor disease outcomes." (PMID 37566060, 2023). "However, CLEC2.Fc efficiently inhibited the expression of proinflammatory cytokines (IL‐6, TNF‐α, IFN‐γ, and IL‐10) and chemokines (CXCL1, CXCL2, CXCL5, CCL2, IP‐10) at day 3 and day 5 post‐infection (blue columns)." (PMID 37211986, 2023). "In addition to CXCL8, SpyCEP cleaves all neutrophil-specific chemokines that possess an ELR motif, namely, CXCL1, CXCL2, CXCL3, CXCL5, CXCL6, and CXCL7, thereby inhibiting the recruitment of neutrophils to sites of infection and inflammation." (PMID 34649250, 2022). "Notably, the NOD-like receptor proteins NOD1 and NOD2 can participate in innate immune responses, and NOD1 stimulates the release of chemokines, such as CXCL-8, CXCL-1, and CXCL-2, which can attract neutrophils to the site of infection." (PMID 35993024, 2022). "Mincle−/− MΦ displayed reductions in neutrophil chemoattractant (Cxcl1) and macrophage chemoattractant (Ccl2) transcription at 4 h post-infection (hpi), after bacterial endosomal escape, along with nonsignificant reductions in Tnf and Nos2." (PMID 36678402, 2022). "Infection, trauma, ischemia, and toxins increase levels of proinflammatory cytokines, including TNF-α, IL-1β, IL-6, IL-18, and chemokines such as C-C motif chemokine ligand 1 (CCL1), CCL5 and C-X-C motif chemokine ligand 1 (CXCL1)." (PMID 36313229, 2022). "Based on our observation of decreased CXCL1 and CXCL2 in fibrotic lungs after infection, we hypothesized that immune cell recruitment to the lungs of these mice might be impaired." (PMID 34990413, 2022).
infection (continued). "Compared with noninfected cells, CXCL1 protein and RNA transcripts were detected at high levels upon infection of WT macrophages but were poorly produced by Casp11−/− cells." (PMID 35588457, 2022). "In addition to IL-6, CXCL1 and CCL2, IL-1β protein levels in PGRN KO kidney were also significantly lower than WT mice at day 9 post-infection when significantly lower fungal burden was observed in PGRN KO mice." (PMID 36121866, 2022). "Heightened colonic cytokine levels in the WT-infected group also correlated with significant increases in serum GCSF, IL-1β, IL-3, IL-6, IL-17, CXCL1, CXCL9, MCP-1, TNF-α and TREM at the peak of infection (48-hours), when compared to the TcdA−TcdB−CDT+ and uninfected groups (p< .05)." (PMID 36045589, 2022). "In addition to human ELR+ CXC chemokines, SpyCEP cleaves the murine CXCL1 and CXCL2 homologues MIP-2 and KC, which signal via mCXCR2 and play a significant role in recruiting neutrophils to the sites of infection in mice." (PMID 34649250, 2022). "Cxcl1 and Cxcl2 regulated by Mir22 and Mir155 are chemokines which signal through CXC receptor 2 to attract neutrophils to the place of inflammation, which is essential to control tissue infection." (PMID 34527215, 2021). "Dnmt3bfl/flCc10Cre mice showed higher levels of CXCL1 when compared with littermate control mice at 6 hours after infection; this difference was not present anymore at 24 hours." (PMID 33793661, 2021). "Blocking the action of CXCL1/CXCL2 by injecting anti-CXCL1 and anti-CXCL2 antibodies 1 h before S. aureus infection significantly suppressed the recruitment of neutrophils to the MZ at 3 h post-infection." (PMID 34040603, 2021). "CXCL1, IL-8, and CXCL5 activate the CXCR2 receptor, the function of which is to recruit neutrophils to the site of inflammation where they play a central role in first-line defences against infection." (PMID 33780519, 2021). "In addition, CXCL1 and CCL2 in infected WT kidneys were described to be detectable as early as 12 h after infection, supporting rapid recruitment of innate myeloid cells." (PMID 33608410, 2021). "Our past studies of adenovirus infection of human corneal fibroblasts in vitro and in a mouse model of adenovirus keratitis in vivo showed early expression of CXCL8 and its murine homologue CXCL1, respectively; and CCL2, and ICAM-1, all within the first day post infection (pi)." (PMID 34960773, 2021). "Indeed, the expression of CXCL1 and CXCL2, neutrophil-attracting chemokines, was significantly upregulated in macrophages upon infection." (PMID 34073501, 2021). "We found that the expression of CX3C subfamily (CX3CL1) and the C subfamily member (XCL1) was only highly increased in the H9N2-infected mice compared to the mock control, but the expression of CCL4, CXCL1, and CXCL2 was significantly increased in both single infection groups." (PMID 33968006, 2021). "Consistent with the lack of a significant difference in the infection phenotype between the WT and Caspase-1/11−/− mice, the levels of the chemokine Cxcl1 were also comparable." (PMID 34011393, 2021). "Dnmt3b ablation in mouse AEC2 did not impact CXCL1 production, neutrophil influx or bacterial clearance after infection with Pseudomonas." (PMID 33793661, 2021). "However, in each case, U288 strains (i) colonised the mouse caecum to a greater level, (ii) induced higher levels of CXCL1 and NOS2 transcripts, and iii) triggered a more severe pathology, compared to that resulting from infection with ST34 strains." (PMID 33893390, 2021). "In addition, CXCL1, CXCL2, and CXCL5 suppress excess CXCL13 expression in macrophages via the CXCR2 axis during the early infection stage." (PMID 34868067, 2021). "PGE2 presented positive correlations with IL-8, CXCL1, and LTB4, in susceptible dogs before infection diagnosis and a negative one with IP-10." (PMID 33617528, 2021).
infection (continued). "PR8 IAV-infected mice lacking type I or III IFN signaling more readily succumb to infection and this correlates with increased CXCL1 production and neutrophil accumulation in the lung compared to wildtype C57BL/6 mice." (PMID 34152253, 2021). "The mRNA expression of various inflammatory cytokines (Il-6, Tnf-α, Ifn-γ, and Ifn-β) and chemokines (Ccl2, Ccl4, Ccl12, Cxcl1, and Cxcl10), but not Il-1β, was elevated in the lungs at 2 dpi, in the early stage of infection." (PMID 34463644, 2021). "Collectively, the infection outcomes of mice of the three genotypes were not consistent with the IL-1β expression levels but consistent with the neutrophil chemoattractant Cxcl1." (PMID 34011393, 2021). "TNF, CCL2, and CXCL1 were mainly produced by ex vivo-restimulated liver-derived Ly6Chi monocytes from E. histolytica-infected male and female mice on Day 3 post-infection (p.i.), rather than by Ly6Clo, Ly6Cneg, Ly6G+, and CD11bneg cells." (PMID 32651360, 2020). "Furthermore, upon infection the bronchoalveolar and thoracic cavity lavage of S100A8/A9-/- mice showed increased concentrations of CXCL-1, CXCL-2, CXCL-5, as well as elastase in comparison to the WT controls." (PMID 32107497, 2020). "At 24 h post infection, significant production of CXCL1 was seen with both HRV-1A and HRV-C15, while at 48 h post infection, all 3 strains of HRV induced significant production of CXCL1." (PMID 32232015, 2020). "Secretions of the chemokines CXCL1 and CCL3 were significantly higher in infected ECD mice compared to infected control mice one-week post infection (p < 0.0001), there was a decrease in the chemokine levels by 2 weeks post infection, which is like the trend observed for mice infected at ZT3." (PMID 32958779, 2020). "The cytokines CXCL8, CCL5 (also known as Regulated on Activation, Normal T Expressed and Secreted, RANTES), tumor necrosis factor α (TNF-α), CXCL1/5 and CCL3 released, promote development of a pro-inflammatory state along with the recruitment of other immune cells to the site of infection." (PMID 33102253, 2020). "Therefore, our data demonstrate that TLR-2 and TLR-4 are indirectly associated with neutrophil migration because the lower levels of CXCL1 and CCL3 in KO animals’ infection site led to an impairment in neutrophil migration." (PMID 33193308, 2020). "IL-1β, CXCL1, CXCL2, and CCL2 expression was significantly higher in the lungs of klotho KO mice infected with A. baumannii than in those of klotho WT mice at 1 day post-infection." (PMID 33329595, 2020). "Thus, the impairment of CXCL1 and CCL3 production in TLR-2KO and TLR-4KO animals affects neutrophil migration to the infection site." (PMID 33193308, 2020). "Because chemokines CXCL1 and CCL3 are known to be important for neutrophil migration, we next measured the levels of CXCL1 and CCL3 in the peritoneal lavage after 3 h of infection." (PMID 33193308, 2020). "To test whether susceptibility could be explained by an overall deficiency in the intestinal immune response we analyzed gene expression for several infection-induced cytokines including TNF, IL-6, S100A, IL-18, and CXCL1." (PMID 32453761, 2020). "Pre-infection blockade of TNFR1 was found to significantly reduce neutrophil number and activation status, consistent with the concomitant reduction of pro-neutrophilic chemokine Cxcl1 and Cxcl2." (PMID 33080861, 2020). "Interestingly, among the unique upregulated genes upon apical infection of HIBCPP cells, we noted CXCL1, CXCL8 and IL-6." (PMID 32872518, 2020). "Further guidance to sites of infection is provided by a family of CXCL8 chemokines originating from concentrated sites of PAMPs and DAMPs, including CXCL1, CXCL2, CXCL3, CXCL5, CXCL6, CXCL7, and CXCL8 (IL-8), which are sensed by CXCR1 and CXCR2 on neutrophils and monocytes." (PMID 30791481, 2019).